IL6 (interleukin 6)
Diseases named in the same sentence as IL6 in open-access papers (continued):
Sharing a sentence is not in itself a finding about the gene and the disease.
COVID-19 (continued). "During a cytokine storm in COVID-19, several inflammatory cytokines are quickly formed, including interleukin 6, tumor necrosis alpha, interleukin 1β, interleukin 12, and interferon gamma, stimulating the secretion of ferritin by hepatocytes, Kupffer cells, and macrophages." (PMID 34840966, 2021). "Also, critically ill COVID-19 patients exhibit a so-called “cytokine storm”, with acute increase in pro-inflammatory cytokines such as IL-6, leading to immune cell infiltration in the lungs." (PMID 34408743, 2021). "Collectively, IL-6 inhibitors could be an option for the treatment of severely ill patients with COVID-19." (PMID 34769508, 2021). "To further investigate the role of these cytokines on T cell phenotype, we also exposed PBMCs isolated from patients with COVID-19 to medium containing their own serum in the presence of blocking antibodies directed against IL-1β, IL-1RA, IL-6, IL-8, or IP-10, added either individually or as a pool." (PMID 34784300, 2021). "Endothelin-1 may also promote endothelial dysfunction, platelet activation, and IL-6 secretion, all detrimental in the setting of COVID-19." (PMID 34441038, 2021). "IL-10, which is known as a suppressor in the initiation phase of inflammation during COVID-19 and correlated strongly with proinflammatory IL-6 (r=0.5, p<0.0001) and TNF-α (r=0.6, p<0.0001), probably performing an immune-inhibitory mechanism as a negative feedback inflammation loop." (PMID 34858428, 2021). "Using Tocilizumab (TCZ), a human IL-6 blockade agent, indicated a reduction in lung lesion opacity, oxygen demand, decrease in C-reactive protein, and normalization of lymphocytes count in 90.5, 75, 84.2, and 52.6% in COVID-19 patients, respectively." (PMID 33761870, 2021). "Early detection of αEp9 Abs in patients could be used to triage and treat COVID-19 prior to the onset of its most severe symptoms; delayed treatments with IL-6-targeting drugs can decrease their efficacy or be counterproductive (31, 37, –, 42)." (PMID 33910993, 2021). "Recently, it had also been shown that the expression of pro-inflammatory cytokines such as IL-6 and IL-8 following MPs formation can exasperate COVID-19 and been proposed to MPs (and its subpopulation) to serve as panel of markers for COVID-19 onset, progression, and severity." (PMID 34176095, 2021). "Several ongoing clinical studies are using anti-IL-6 in therapeutical protocols for COVID-19." (PMID 34065210, 2021). "This drug blocks pro-inflammatory activity of IL-6 and could be effective in the management of COVID-19 patients." (PMID 33761870, 2021). "COPD patients with severe COVID-19 had elevated serum levels of various inflammatory cytokines including IL-2R, IL-6, IL-8, IL-10, and TNF-α suggesting there may be global alterations in the immune response." (PMID 34262047, 2021). "In a recent study 1,484 patients with suspected or confirmed COVID-19 were investigated with a conclusion that the levels of IL-6 and TNF alpha in serum at presentation are predictive of COVID-19 survival and mortality, independently of demographics and comorbidities." (PMID 34149697, 2021). "Indeed, in a first pilot study in COVID-19 patients requiring intensive care, high-dose IV vitamin C significantly improved oxygenation, reduced organ-damaging cytokine storm (IL-6), and showed a trend towards reduced mortality in severely ill patients." (PMID 33807280, 2021). "Moreover, other authors have reported a direct correlation between IL-6 levels and inflammasome hyperactivation, typically occurring in severe cases of COVID-19." (PMID 34829906, 2021). "Additionally, IL-6 levels in the setting of COVID-19 have been reported to be elevated in several studies and have been shown to correlate with mortality." (PMID 34195234, 2021). "IL-1β and its downstream effectors IL-6 and TNF-α are linked to the exacerbation of COVID-19." (PMID 34150848, 2021).
COVID-19 (continued). "Therefore, we monitored serum IL-6 levels in patients with COVID-19 to better understand prognosis and to implement effective treatment." (PMID 34222268, 2021). "The effects of two important therapy methods, namely, the tocilizumab and convalescent plasma therapy (CPT) on IL-6 levels were also analyzed, which demonstrated that both methods were beneficial to patients with COVID-19, as indicated by a decrease in IL-6 levels." (PMID 33746945, 2021). "Thus, our findings further highlight the need for clinicians to pay close attention to COVID-19 patients with elevated serum IL-6 levels at hospital admission, especially those with coexisting MAFLD." (PMID 33763027, 2021). "NDG from severe/critical COVID-19 patients may be primed in vivo to spontaneously produce NETs, since they are exposed to IL-6, IL-2, IL-7, TNF, CXCL10, MCP-1, MIP1a, GM-CSF and M-CSF during the cytokine storm." (PMID 34685525, 2021). "The top-weighted features IL-6 (R = 0.55), PCT (R = 0.55), CRP (R = 0.52), IL-2R (R = 0.45), and Th/Ts (R = 0.23) were consistent with previously reported risk factors intimately associated with poor outcome of COVID-19." (PMID 33602326, 2021). "Importantly, the cytokine profile described in COVID-19-Patients shows large similarities with the cytokine profile of α7nAChRs dysregulated macrophages i.e. massively secreting IL-1β, IL-6, tumor necrosis factor alpha (TNF α) α and IL-18 among others." (PMID 33510335, 2021). "Although IL-6 was equally elevated both in patients with COVID-19 or non-COVID-19 (e.g., influenza), only GM-CSF was prominently elevated in patients with severe COVID-19, supporting the notion that GM-CSF serves as an important biomarker of COVID-19 disease severity." (PMID 34022793, 2021). "Elevated HMGB1, NLRP3 and IL-6 levels could be discriminative markers for COVID-19 headache and may have implications for prevention and also for other secondary headaches related to other systemic viral infections." (PMID 34384355, 2021). "GDF-15 and IL-6 derived from proteomics analysis were related with disease severity of COVID-19." (PMID 35095877, 2021). "Similarly, a study from China revealed correlations of IL-6 and procalcitonin levels with COVID-19 severity, namely that those with the highest levels of these two biomarkers exhibited significantly increased disease severity." (PMID 34684107, 2021). "An analysis in the future on data from a larger number of patients can be used to explore whether longitudinal IL6 testing can be a useful biomarker for COVID-19 severity." (PMID 33723251, 2021). "Moreover, interleukin 6 (IL-6) receptor blockade seems to be a promising treatment for a specific group of COVID-19 patients." (PMID 34113503, 2021). "In view of the pivotal role of cytokines (especially IL-6) and NETosis in biology of COVID-19 host response, we performed a deep and focussed investigation into IL-6, NETosis, complement and coagulation in published data from multiple patients of COVID-19 with varying illness severity." (PMID 34775962, 2021). "Regarding the COVID-19 laboratory biomarkers, the mean lymphocyte count was low (0.63 [0.43–0.90] × 109/L) and the plasma levels of D-dimer, ferritin, and IL-6 were notably elevated with median values of 1.12 [0.59–3.52] mg/L, 1389.0 [821.0–2250.0] ng/mL and 114.0 [47.5–181.4] pg/mL, respectively." (PMID 34517881, 2021). "In addition to vascular permeability, the IL-6 can foster endothelial dysfunction; hence, IL-6 is an attractive drug target for mitigating the complications of COVID-19." (PMID 34159203, 2021). "It seems likely that the spike in IL-6, secreted by the macrophages responding to the viral entry, triggers NETosis in the patients with severe COVID-19, leading to a complex interaction among NETosis, complement and coagulation pathways, pulmonary immune thrombosis and acute respiratory distress." (PMID 34775962, 2021).
COVID-19 (continued). "Furthermore, a recent prospective cohort study indicated that high levels of IL-6 and D-dimer reflected systemic inflammation and thrombotic condition and predicted in-hospital mortality of COVID-19." (PMID 34803441, 2021). "As is the case with COVID-19, there is an increase in IL-1β, IL-6, and C-reactive protein (CRP)." (PMID 34367545, 2021). "Therefore, we conducted a meta-analysis to determine the role of lymphocyte and platelet counts as well as interleukin-6 levels as predictors of death in patients with COVID-19." (PMID 34938342, 2021). "Recent studies have indicated that tocilizumab administered to severe COVID-19 patients with significant elevated IL-6 levels due to cytokine storm may improve their prognosis." (PMID 34287285, 2021). "Thus, it is suitable for in vivo and continuous monitoring of targeted biomarkers and is especially viable for application in the continuous monitoring of IL-6 elevation for COVID-19 patients." (PMID 34205852, 2021). "In the hyperinflammatory phase, patients with severe COVID-19 exhibit higher levels of IL-2, IL-6, IL-7, IL-10, IP-10, MCP1, TNF-α, macrophage inflammatory protein 1 alpha (MIP1A), and granulocyte-colony stimulating factor (G-CSF) than patients with moderate infections (early inflammatory phase)." (PMID 34220861, 2021). "Reports exist of IL-6 and IL-15 upregulation in patients with severe presentations of COVID-19." (PMID 34829906, 2021). "Given ongoing clinical trials that target the effects of IL-6, complement activation and NETs in COVID-19 patients future approaches that block necroptosis or MT-DAMP recognition could also be warranted." (PMID 33444289, 2021). "Severe COVID-19 results in early interleukin (IL)-6, IL-10 and IL-1β-enhanced hyperinflammation." (PMID 34630377, 2021). "Several proinflammatory cytokines, such as tumor necrosis factor-α (TNF-α), interleukin (IL) 1β and chemotactic cytokines (e.g., IL-8 and macrophage chemoattractant protein-1 (MCP-1)) are upregulated during COVID-19, leading to a sustained increase in IL-6 levels." (PMID 34830648, 2021). "Meanwhile, active AOSD patients had even higher IL-6 levels than severe COVID-19 patients." (PMID 34367188, 2021). "Moreover, it has been observed that the most severe cases of COVID-19 are associated with a reduction in CD4+ T, T-lymphocytes, CD8+ T cells and an increase in levels of C-reactive protein, D-dimer, ferritin, IL-6, IL-2R40." (PMID 34824310, 2021). "Another study observed that COVID-19 patients with hypertension on ACEIs or ARBs treatments had a reduced frequency of disease severity and exhibited a tendency for reduced serum levels of IL-6." (PMID 34806090, 2021). "High levels of IL-6 are often associated with the acute severe systemic inflammatory response known as a cytokine storm, and persistent elevation of IL-6 is a predictive factor of poor prognosis of patients with ARDS and COVID-19 (7, 12, –, 14)." (PMID 34634929, 2021). "Actually, several studies reported an increased level of IL-6 also in other different clinical settings such as sedentary behavior, obesity, diabetes, cardiovascular diseases, cancer, and recently in COVID-19 patients with poor outcomes, all characterized by a high mortality rate." (PMID 33815869, 2021). "Of note, the percentages of both IL-6 and uric acid (UA) levels in survived COVID-19 patients were above 90%, suggesting that these two factors have a good specificity when used as indicators for COVID-19 mortality." (PMID 33679237, 2021). "The use of metalloproteinase 17 (ADAM17) or soluble glycoprotein 130 fused chimera (sgp130Fc) to specifically inhibit pathological IL-6 trans-signaling in patients with severe COVID-19 promises to be a more effective and safer strategy to ameliorate disease states." (PMID 33628091, 2021).
COVID-19 (continued). "One of the key contributing factors for the higher mortality and morbidity in COVID-19 patients is excess local production of pro-inflammatory cytokines, such as IL-1β, IL-6, IL-8 and TNF in key organs (heart, lungs and liver), which is termed a cytokine storm." (PMID 34422917, 2021). "A recent study confirmed the role of IL-6 in severe COVID-19 cases by immune analysis, suggesting that Th1 cells and monocytes could express high level of IL-6, resulting in deteriorating the tracheobronchial epithelial cells and aggravating the disease." (PMID 34488665, 2021). "Furthermore a variety of biomarkers, including levels of d-dimer, high-sensitivity cardiac troponin I, serum ferritin, lactate dehydrogenase, and IL-6 were significantly elevated in the most severe COVID-19 cases which resulted in death." (PMID 33816549, 2021). "Although overproduction of IL-6 mediates the low HLA-DR expression on CD14+ monocytes of patients with severe COVID-19, anti-IL6 therapy has been unsuccessful in showing improved outcomes in COVID-19, highlighting the urgent need for elucidating the underlying mechanisms." (PMID 33765435, 2021). "As it was shown for COVID-19 infection that levels of IL-6, along with IL-8 and TNF-α, were powerful predictors of severity and survival at the time of hospitalization, using IL-6 inhibitors could be a promising therapy against sever COVID-19." (PMID 33441142, 2021). "However, its decrease in COVID-19 patients significantly increases the secretion of pro-inflammatory factors such as IL-6, TNF-α, MCP-1, and IL-1 β, and decreases the secretion of IL-10 and transforming growth factor-β (TGF-β)." (PMID 35062245, 2021). "Moreover, these herbs suppressed pro-inflammatory cytokines including IL-6 or TNF-α, which were both identified in the cytokine storm of acute respiratory distress syndrome, a major cause of COVID-19 death." (PMID 35401158, 2021). "Cytokine storms with significant increases in IL-6 and IL-10 often occur in patients with severe COVID-19 and may play an important role in the development of lymphopenia, high neutrophils, and high mononuclear macrophages." (PMID 34712741, 2021). "In addition, COVID-19 patients with severe disease have been shown to suffer from a rapid and excessive production of harmful pro-inflammatory cytokines (IL6, IL1-β, and TNF-α), or “cytokine storm”, triggered by the innate immune response against the virus." (PMID 34031383, 2021). "Levels of IL-6 and other cytokines are not only prominent in patients with severe COVID-19 disease but could have profound CV consequences in patients with COVID-19." (PMID 34442038, 2021). "Moreover, analysis revealed a positive correlation between the serum values of IL-33 and IL-12 (p = 0.001), IL-33 and IL-6 (p = 0.001), and IL-6 and IL-12 (p = 0.001) in patients with COVID-19." (PMID 34917631, 2021). "In short, IL-6 plays a key role in cytokine storm of COVID-19 pathogenesis." (PMID 37287491, 2021). "Many inflammatory factors, including IL-6 and interleukin-10 (IL-10), are closely related to COVID-19 and have diagnostic value, but neither IL-6 nor IL-10 were detected in the patients of this study." (PMID 33534722, 2021). "Next, the ROC curve was drawn for the severity of COVID-19 based on the levels of IL-6." (PMID 33390771, 2021). "Indeed, elevated IL-6 levels, which correlate with COVID-19 severity, have been associated with depression and alterations in activity in the subgenual cingulate cortex." (PMID 34349633, 2021). "Moreover, low levels of IFN-I and ISGs, along with an increase in IL-6 and inflammatory responses, were observed in peripheral blood samples from patients with severe or critical COVID-19." (PMID 34001144, 2021). "IL-6 concentration has been shown to be higher in patients with severe COVID-19." (PMID 34065057, 2021). "This suggests that elevated IL-6 levels may be a marker of poor prognosis in patients with COVID-19." (PMID 34724920, 2021).
COVID-19 (continued). "Anti-IL-6 mAbs have also been shown to enhance clinical outcomes in COVID-19 patients." (PMID 35822018, 2021). "Since IL6 plays a central role in the acute inflammatory response, its potential inhibition could significantly improve prognosis in COVID-19 patients." (PMID 33693014, 2021). "Also, a fatal outcome has been observed in patients with severe COVID-19 with kinetic variations in IL-6, IL-8, and IL-10, independently of sex, age, absolute lymphocyte count, direct bilirubin, hypertension, and chronic obstructive pulmonary disease." (PMID 34646263, 2021). "We also found increased levels of IL-6 in severe COVID-19 patients compared with mild patients." (PMID 33633875, 2021). "Sequential monitoring and timely intervention of IL-6 may favor the clinical management of COVID-19." (PMID 33390771, 2021). "Indeed, in COVID-19 patients, significant differences in IL-6 plasmatic levels were observed at different stage of disease with a higher expression in severe cases." (PMID 33544720, 2021). "However, additional investigation into the lung-specific cellular source of the proinflammatory cytokines typical of severe COVID-19, including IL-6, tumor necrosis factor–α (TNF-α), IL-1β, and IL-17A, is needed." (PMID 33622974, 2021). "The Food and Drug Administration (FDA) has approved antiviral drug (remdesivir), corticosteroid (dexamethasone, prednisolone, and methylprednisolone), and monoclonal antibodies, particularly IL-6 antibodies (tocilizumab, siltuximab, and anakinra), for the treatment of COVID-19." (PMID 34721573, 2021). "Cumulative reports correlate the severity of COVID-19 with the excessively-heightened level of pro-inflammatory mediators including interleukin 1 (IL-1), interleukin 6 (IL-6), tumor necrosis factor-alpha (TNF-α), alongside multiple agents, lists of which reported elsewhere." (PMID 33888147, 2021). "Moreover, to define the roles of IL-6 and RNAaemia as pathological markers of COVID-19 deterioration, further investigations involving autopsy, biopsy, or BAL studies should be undertaken." (PMID 34379684, 2021). "The significantly decreased levels of CD4+ T lymphocytes and ratio of CD4+/CD8+ lymphocytes and the significantly increased levels of TNF-α and IL-6 in the peripheral blood can be used as important laboratory indicators to assess the severity of COVID-19 in patients." (PMID 32976531, 2020). "In addition, the serum levels of IL-6 and IL-2R in COVID-19 patients are positively correlated with the severity of the disease, suggesting that the cytokine storm is positively correlated with the severity of COVID-19 infection." (PMID 33002109, 2020). "Thus, our studies suggest that IL-6 and IL-8 can be respectively used as biomarkers for severe COVID-19 patients and for COVID-19 disease prognosis." (PMID 33488599, 2020). "Interestingly, it has been reported that levels of TNF-α and IL-1β, and some chemotactic cytokines (IL-8 and MCP-1) rise early in COVID-19 hypercytokinemia, facilitating a subsequent sustained increase in IL-6." (PMID 33292350, 2020). "Lowering IL-6 or other inflammatory cytokines in COVID-19 patients is reasonable, but the timing may be critical as early treatment may be detrimental." (PMID 32704352, 2020). "In severe cases of SARS, MERS, and COVID-19, the secretion of a number of pro-inflammatory cytokines, including IL-6, IL-12, IFN-γ, and TNF-α, was increased compared to mild cases, suggesting that an overactive cytokine response plays a role in disease severity." (PMID 33374514, 2020). "Indeed, SAgs induce an inflammatory cytokine signature similar to that which predicts severity and death in COVID-19, including IL-6, TNFα, IL-8, and IL-1β." (PMID 32989130, 2020). "Solid published results demonstrated a close relationship between TCZ action and an increased Trp catabolism in different inflammatory settings driven by IL-6, suggesting the possibility and relevance of monitoring Trp metabolism in COVID-19 patients on TCZ therapy." (PMID 32636755, 2020).